UGT1A8 (UDP glucuronosyltransferase family 1 member A8)
Description:
[Isoform 1]: UDP-glucuronosyltransferase (UGT) that catalyzes phase II biotransformation reactions in which lipophilic substrates are conjugated with glucuronic acid to increase the metabolite's water solubility, thereby facilitating excretion into either the urine or bile. Essential for the elimination and detoxification of drugs, xenobiotics and endogenous compounds. Catalyzes the glucuronidation of endogenous steroid hormones such as androgens and estrogens. Produces dihydrotestosterone (DHT) diglucuronide from the DHT after two subsequent glucoronidation steps. Involved in the glucuronidation of the phytochemical ferulic acid at the phenolic or the carboxylic acid group. Also catalyzes the glucuronidation of the isoflavones genistein, daidzein, glycitein, formononetin, biochanin A and prunetin, which are phytoestrogens with anticancer and cardiovascular properties. Involved in the glucuronidation of the AGTR1 angiotensin receptor antagonist caderastan, a drug which can inhibit the effect of angiotensin II. Also metabolizes mycophenolate, an immunosuppressive agent. [Isoform 2]: Lacks UGT glucuronidation activity but acts as a negative regulator of isoform 1.
Synonyms: UDPGT 1-8; UGT1-08; UGT1.8; UGT-1H; UGT1H; UDPGT; UGT1A8S
Tractability: Small molecule: a high-quality ligand is known. Antibody: UniProt predicts a signal peptide or a membrane-spanning region. PROTAC: a small molecule that binds it is known.
Target class: Enzyme; Transferase
Safety:
Unwanted effects reported when the protein is acted on. In parentheses: how it was acted on, where the effect was seen, and who reports it.
a diminished estimated glomerular filtration rate and transient proteinuria (source: ClinPGx)
adverse drug reactions (source: ClinPGx)
adverse effects (source: ClinPGx)
adverse reactions (source: ClinPGx)
better response (source: ClinPGx)
cardiotoxicity (source: ClinPGx)
diarrhea (source: ClinPGx)
diarrhoea (source: ClinPGx)
diminished estimated glomerular filtration rate and transient proteinuria (source: ClinPGx)
hand-foot syndrome (source: ClinPGx)
hyperbilirubinemia (source: ClinPGx)
hyperprolactinemia (source: ClinPGx)
liver failure (source: ClinPGx)
nephrolithiasis (source: ClinPGx)
neutropenia (source: ClinPGx)
severe neutropenia (source: ClinPGx)
sorafenib-induced grade 2 diarrhea (source: ClinPGx)
worse response (source: ClinPGx)
Gene: Protein-coding gene on chromosome 2 (233,617,633 to 233,773,300, forward strand). Ensembl gene ENSG00000242366.
Subcellular location: Endoplasmic reticulum membrane
Pathways (Reactome):
Drug ADME: Aspirin ADME
Metabolism: Glucuronidation
Gene Ontology:
Molecular function: enzyme binding; enzyme inhibitor activity; fatty acid binding; glucuronosyltransferase activity; protein homodimerization activity; steroid binding; retinoic acid binding; protein heterodimerization activity; UDP-glycosyltransferase activity
Biological process: flavone metabolic process; flavonoid metabolic process; steroid metabolic process; xenobiotic metabolic process; cellular response to glucocorticoid stimulus; coumarin metabolic process; estrogen metabolic process; fatty acid metabolic process; liver development; negative regulation of fatty acid metabolic process; negative regulation of steroid metabolic process; retinoic acid metabolic process; monocarboxylic acid metabolic process
Cellular component: endoplasmic reticulum; endoplasmic reticulum membrane
Genetic constraint (gnomAD): Loss-of-function variants: 39 observed, 47.06 expected, observed/expected ratio (o/e) 0.83, 90% interval 0.64 to 1.08. The upper end of that interval is the gene's LOEUF score, 1.08, which puts it in group 4 of 6, group 1 being the genes least tolerant of losing a copy. Missense variants: 719 observed, 693.26 expected, observed/expected ratio (o/e) 1.04, 90% interval 0.98 to 1.1. Synonymous variants: 275 observed, 259.36 expected, observed/expected ratio (o/e) 1.06, 90% interval 0.96 to 1.17.
Homologues: Orthologues: dog UGT1A6 (81% identical), mouse Ugt1a9 (79% identical), mouse Ugt1a10 (79% identical), mouse Ugt1a7c (79% identical), mouse Ugt1a8 (78% identical), zebrafish ugt2a7 (40% identical), zebrafish si:ch73-334d15.1 (39% identical), zebrafish ugt2b5 (38% identical), zebrafish ugt2b1 (38% identical), zebrafish ugt5g1 (37% identical), zebrafish ugt5a2 (36% identical), zebrafish ugt5c1 (36% identical), and 98 more. Paralogues in human: UGT1A9 (95% identical), UGT1A10 (95% identical), UGT1A7 (95% identical), UGT1A5 (69% identical), UGT1A3 (68% identical), UGT1A4 (68% identical), UGT1A6 (68% identical), UGT1A1 (67% identical), UGT2B10 (44% identical), UGT2B17 (44% identical), UGT2B15 (43% identical), UGT2B4 (43% identical), and 9 more.
Diseases named in the same sentence as UGT1A8 in open-access papers:
UGT1A8 is named in the same sentence as 18 diseases in open-access papers, as found by Europe PMC text mining. Sharing a sentence is not in itself a finding about the gene and the disease. The quoted sentences say what the papers report.
breast carcinoma (5 papers, 2012 to 2022). "Furthermore, the UGT1A8 polymorphism is associated with breast cancer and leads to an increased risk of breast cancer cell malignancy." (PMID 36741721, 2022). "Our results demonstrate that the mRNA levels of the UGTs analyzed, with the exception of UGT1A8, which was not expressed, are differentially down-regulated in breast cancers as compared to normal breast tissue specimen from AA and EA women in this study." (PMID 30349745, 2012). "The mRNA expression of all UGTs studied, with the exception of UGT1A8, was detected in the majority of normal breast tissue specimens; however, several UGT mRNAs were either down-regulated or not expressed in the majority of breast cancers." (PMID 30349745, 2012).
breast tumor (1 paper, 2012). "In the present study, we characterized the mRNA expression of UGT1A1, UGT1A4, UGT1A8, UGT1A10, and UGT2B7 in normal and breast tumor tissues from AA and EA women." (PMID 30349745, 2012).
colorectal cancer (1 paper, 2013). A primary or metastatic malignant neoplasm that affects the colon or rectum. "Another strength of the study is the large sample size with controls to evaluate the role of UGT1A8 polymorphism in colorectal cancer." (PMID 23468910, 2013). "Based on earlier reports, we recognized changes of expression and function of UGT1A8 might be a risk factor of colorectal cancer." (PMID 23468910, 2013). "However, little is known of the correlation between UGT1A8 genotype and susceptibility of colorectal cancer for Chinese, which is the motivation behind this study." (PMID 23468910, 2013).
endometrial cancer (1 paper, 2024). Primary or metastatic malignant neoplasm involving the endometrium (mucous membrane that lines the endometrial cavity). "UGT1A8 expression is altered in endometrial cancer and amino acid substitutions in it may modulate estradiol metabolism leading to increased risk of breast and endometrial cancer." (PMID 39132489, 2024).
ovarian carcinoma (1 paper, 2020). A malignant neoplasm originating from the surface ovarian epithelium. "There are no reports to date regarding UGT1A8 in ovarian cancer." (PMID 31895688, 2020).
schizophrenia (1 paper, 2021). A major psychotic disorder characterized by abnormalities in the perception or expression of reality. "Labad and collaborators demonstrated the relevance of genetic variants in UGT1A8 and oestrogen receptor 1 genes in the modulation of response to raloxifene in postmenopausal women with schizophrenia." (PMID 34575626, 2021).
cancer (3 papers, 2013 to 2022). A tumor composed of atypical neoplastic, often pleomorphic cells that invade other tissues. "In addition, the identification of tissue-specific expression of UGT1A8 implies that the regulatory mechanisms may be indicative of the evolutionary development and the biological basis determining individual variations in cancer risk." (PMID 23468910, 2013). "The high expression of UGT1A8, UGT8, UGT1A7, UGT2A3, and UGT2B15 in these cancers and its relation to good patient prognosis is very interesting and deserves further investigation." (PMID 36741721, 2022).
UGT1A8 also shares sentences with these, for which no sentence is quoted: cholelithiasis (1 paper); colon adenocarcinoma (1); coronary heart disease (1); diabetes mellitus (1); diarrheal disease (1); ischemic stroke (1); kidney disease (1); lung carcinoma (1); metabolic disorders (1); prostate carcinoma (1); respiratory infection (1).